APC (APC regulator of Wnt signaling pathway)
Diseases named in the same sentence as APC in open-access papers (continued):
Sharing a sentence is not in itself a finding about the gene and the disease.
lung carcinoma (continued). "Tobacco smoking has been shown to be associated with an increased DNAm of specific genes in somatic analyses of lung cancers (e.g., p16, APC, MGMT, ANK1, MTHFR)." (PMID 35205708, 2022). "Crossing this mutation (Ndst1f/f CD11cCre+) onto a model of inducible spontaneous Kras mutant lung cancer [CCSP-rtTA; (tetO7) CMV-Kras-G12D] allowed us to examine how the APC mutation affects the formation and growth of early lung carcinoma." (PMID 34715561, 2021). "Based on previous studies and our investigation, we believed that the methylation of 6 tumor suppressor genes (FHIT, p16, MGMT, RASSF1A, APC, and DAPK) was associated with the prognosis of lung cancer patients." (PMID 34257703, 2021). "In another study by Lin and co-workers, miR-3607 was upregulated in lung cancer tissues and cells, and miR-3607 overexpression promoted cell proliferation by suppressing APC." (PMID 32404179, 2020). "Lung cancer patients, as well as patients with other types of epithelial cancers, showed hypermethylation of the APC promoter compared to healthy controls." (PMID 31108839, 2019). "Our study provided strong evidence supporting APC mutations-directed applications of anti-DKK2 targeted therapy in a wide range of cancer types, including lung cancer." (PMID 31372243, 2019). "We found that compared to recurrence patients, Met, ALK, APC, PTEN, ERBB4, NF1, and other genes in recurrence-free patients never mutated, involving multiple tumor suppressor genes and lung cancer-driven genes." (PMID 31182981, 2019). "APC hypermethylation occurs during the early stages of tumorigenesis and has been extensively studied in lung cancer." (PMID 30871143, 2019). "Our studies indicated that DKK2 plays similar roles in both colorectal and lung cancer when they carry APC mutants." (PMID 31372243, 2019). "Conversely, the Burkitt lymphoma cell line-specific SNP, APC, demonstrated a 20-fold or greater suppression following xMD (lymphoma/lung carcinoma cell line—46.6% vs. 2.3; lymphoma/melanoma cell line—52.3% vs. undetectable)." (PMID 26999048, 2016). "Several studies have found differences in the methylation frequencies of APC or RASSF1A among the particular histological types of lung cancer." (PMID 26550041, 2015). "Such previous studies identified the RASSF1A, PITX2, SHOX2, TFPI-2, FHIT, p16, CDH13, and APC genes as predictors of recurrence of lung cancers." (PMID 23544068, 2013). "For example, differential expression of several WNT components including WNT1, WNT2, WNT7A, DVL3, β-CATENIN and APC, have been reported in normal lung tissues and lung cancers, particularly in NSCLC (non-small cell lung cancer)." (PMID 22846383, 2012). "APC promoter hypermethylation has also been seen in lung tissue in healthy subjects exposed to cigarette smoke and blood in lung cancer patients." (PMID 21878113, 2011). "Dysregulation of canonical Wnt signaling has also been demonstrated in lung cancer, mediated through epigenetic silencing of negative regulators such as SFRP1 and WIF-1 or rare mutations in APC and β-catenin." (PMID 22016777, 2011). "Biologically, previous studies have shown that APC is associated with cancer recurrence, and AKT1 are associated with several different cancers, such as breast, colorectal, and lung cancers." (PMID 19956614, 2009). "In lung carcinoma, APC promoter methylation has been correlated with smoking status and non-metastatic cases, while methylation in APC has been observed to be associated with an increased risk of prostate cancer-specific mortality." (PMID 38886806, 2024).
lung carcinoma (continued). "APC mutations could be a major biomarker for distinguishing MRC from PEAC, although they are also found in approximately 6% of lung cancer." (PMID 37374074, 2023). "As a consequence, most of the primary NSCLCs contain abnormally methylated APC gene promoters, which may serve as a biomarker of primary lung cancer." (PMID 37901797, 2023). "The aberrant methylation of various frequently methylated genes in lung cancer, including retinoic acid receptor 2 β (RAR-β2), H-cadherin, adenomatous polyposis coli (APC), and Ras association domain family member 1 (RASSFF1A), has also been described in bronchial epithelial cells of heavy smokers." (PMID 35313869, 2022). "Methylation levels in adenomatous polyposis coli (APC), homeobox gene A9 (HOXA9), retinoic acid receptor beta 2 (RARβ2), and Ras association domain-containing protein 1 (RASSF1A) were assessed as a novel non-invasive method for lung cancer subtyping." (PMID 32326172, 2020). "Abnormal methylation of APC gene promoter occurs in lung cancer patients." (PMID 31839821, 2019). "Results in vitro showed that knockdown of DNMT1 by siRNA, similar to the 5-Aza-CR, could re-express RASSF1A and APC by demethylating their promoter regions, and could promote apoptosis, inhibit proliferation and migration of two lung cancer cell lines." (PMID 28938637, 2017). "Although LOH of the APC gene is a common finding in lung cancer, point mutations of this tumor suppressor have not been frequent." (PMID 24933634, 2014). "Together, our findings provide evidence that Cdc20/APC/C/securin-dependent signaling is a key regulator of cell survival, and its disruption promotes premature senescence in normal lung cells and induces apoptosis in lung cancer cells that have bypassed the senescence barrier." (PMID 35988650, 2022). "Furthermore, the ability of migration was assessed by transwell assay which demonstrated that siRNA-DNMT1 could also impair the capability of migration of two lung cancer cell lines via APC and RASSF1A." (PMID 28938637, 2017). "Moreover, we demonstrated that knockdown of DNMT1 in vivo could also enhance the RASSF1A and APC expression via demethylation, and delayed the lung cancer growth with reduced adverse side effects." (PMID 28938637, 2017). "Therefore, our APC/RASSF1A methylation application for lung cancer prognosis is reliable." (PMID 26550041, 2015). "Quantitative analysis of total plasma DNA and plasma APC/RASSF1A methylation provide a real-time synchronous rapid monitoring indicator for therapeutic outcomes of advanced lung cancer, which could be a reference or supplementary guidelines in evaluating chemotherapy effects." (PMID 26550041, 2015). "As the epigenetic silencing of key tumor suppressor genes, such as APC and p16INK4A, is a common event in lung carcinogenesis and miRNA expression is altered in lung cancer, some miRNAs are thought to be silenced by DNA methylation or histone modification in lung cancer." (PMID 24348521, 2013). "It has been reported that in lung cancer, mutations in the APC gene are not frequent." (PMID 16451736, 2006). "In clinical practice, many of these DMRs have the potential to predict disease progression, including in patients with stage IV lung cancer (SHOX2, RARB/RASSF1A, RARB, RASSF1A/APC, DCLK1, BRMS1, SOX17, SFN, CHFR, and APC/RASSF1A/CDH13/CDKN2A)." (PMID 36765815, 2023). "In lung cancer, genes with methylated specific CpG islands included CDKN2A, RASSF1A, RARbeta, MGMT, GSTP1, CDH13, APC, DAPK, TIMP3, etc." (PMID 36875059, 2023). "The methylation frequencies of 6 genes (FHIT, p16, MGMT, RASSF1A, APC, DAPK) in lung cancer patients, the basic clinical information, and tumor marker levels of these patients were analyzed." (PMID 34257703, 2021).
lung carcinoma (continued). "Abnormal methylation frequencies in the promoter regions of APC and DAPK genes lend a hand for the diagnosis of lung cancer." (PMID 34257703, 2021). "This study identified FHIT, MGMT, P16, RASSF1A, APC, and DAPK as methylation markers of lung cancer through literature review and previous studies." (PMID 34257703, 2021). "Increased methylation levels have been detected in APC, MLH1, and CDKN2A genes in industrial workers with lung cancer." (PMID 30871143, 2019). "We here showed that, in lung cancer, siRNA-DNMT1 in vitro demethylated the RASSF1A and APC to restore its mRNA and protein expression, and induce apoptosis and the cell proliferation and migration were constricted in vitro." (PMID 28938637, 2017). "Abundant evidence manifests that a variety of well-known DNA methylations can be used as a promising biomarker for the early diagnosis of lung cancer, such as p16, RASSF1A, APC, MGMT, DAPK and RARβ." (PMID 28644424, 2017). "Many studies have shown the high methylation frequency of APC and RASSF1A in the plasma of lung cancer patients." (PMID 26550041, 2015). "We studied the methylation status of five genes, p16INK4a, RASSF1A, APC, RARβ and CDH13, that are frequently methylated in lung cancers and that are considered to play an important role in the molecular pathogenesis of lung cancers." (PMID 15266335, 2004). "The present study examined the relationship between methylation of five genes (p16INK4a, RASSF1A, APC, RARβ and CDH13) and patient survival in 351 cases of surgically resected lung cancers." (PMID 15266335, 2004). "For instance, methylation levels of APC, HOXA9, RARβ2 and RASSF1A could assist in better defining lung cancer subtypes (SCLC vs. NSCLC) and stage to develop corresponding treatment plans." (PMID 35205708, 2022). "Moreover, tumor suppressor genes such as p16, APC, and MGMT were substantiated to be hypermethylated in lung cancer tissue." (PMID 34257703, 2021). "Numerous studies showed that in lung cancer, the hypermethylation modification of the CpG island in promoter regions of tumor suppressor genes, such as FHIT, p16, MGMT, RASSF1A, APC, and DAPK, leads to the occurrence of lung cancer and poor prognosis in lung cancer patients." (PMID 34257703, 2021). "Therefore, we detected the quantitative methylation levels of APC and RASSF1A before and 24 h after the chemotherapy cycles to evaluate tumor response in lung cancer patients." (PMID 26550041, 2015). "While CDKN2A, DAPK1 and APC are found hypermethylated both in smoking and non-smoking lung cancer patients others, like APC, FHIT, RASSF1A or CCND2 are strictly correlated with smoking." (PMID 23086271, 2013). "Furthermore, sputum specimens from patients with lung cancer also contained high levels of methylated APC in NSCLC in comparison with adjacent noncancerous tissue." (PMID 37901797, 2023).
lung carcinoma (continued). "Several combinations of differentially methylated gene promoter regions were found to be more effective than single gene promoters (RASSF1A/RARB2, SHOX2/PTGER4, RTEL1/PCDHGB6, HOXD10/PAX9/PTPRN2/STAG3, APC/AIM1/CDH1/DCC/MGMT/RASSF1A) in distinguishing lung cancer patients from noncancerous controls." (PMID 36765815, 2023). "“PanCancer” panel (APC, FOXA1, RASSF1A) detected cancer with 72.4% sensitivity, 73.5% specificity and 72.8% accuracy.“CancerType” panel (SCGB3A1, SEPT9, and SOX17) discriminated TOO with 80.0%, 98.9%, and 85.1% specificity for breast, colorectal, and lung cancer, respectively." (PMID 36980276, 2023). "Furthermore, Met, ALK, APC, PTEN, ERBB4, NF1, and other genes, involving multiple tumor suppressor genes and lung cancer-driven genes, did not mutate in recurrence-free patients when compared with recurrent patients." (PMID 31182981, 2019). "In specimens of biopsies and serum from early‐stage lung cancer patients, higher levels of APC gene methylation were detected than in healthy individuals (nonmethylated APC gene), and there may be a correlation between advanced lung cancer stages and hypermethylation of the APC gene." (PMID 37901797, 2023). "Moreover, an upregulation of APC and β-catenin was shown to significantly increase the levels of matrix MMP-9 and MMP-2 (members of the metalloproteinase family) expression and downregulate E-cadherin, Snail1, and Zeb1 expression, which ultimately resulted in EMT and bone metastasis in lung cancer." (PMID 34568020, 2021). "We found siRNA-DNMT1, resemble to the 5-Aza-CR, could effectively demethylate the TSGs (e.g. RASSF1A and APC) to recover the tumor suppressive ability, but the treatment of siRNA-DNMT1 had less cytotoxicity than 5-Aza-CR which showed the potential superiority in lung cancer-therapy." (PMID 28938637, 2017). "The most frequently analyzed genes like p16, DAPK, APC, RASSF1A, MGMT, FHIT, RARß and GSTP1 were applied as a means of detecting lung cancer or as prognostic factor but none of them had been used for therapy monitoring." (PMID 25675432, 2015).
prostate carcinoma (89 papers, 2009 to 2025). A carcinoma that arises from epithelial cells of the prostate gland. "In prostate cancer, APC loss is also linked to homozygous deletion and truncation mutations in up to 7% of primary and 10.6% of metastatic cases, resulting in the accumulation of β-catenin and elevated Wnt signaling." (PMID 35204808, 2022). "The association of APC promoter methylation with reduced survival has also been reported for other cancer types, such as non-small cell lung cancer and prostate cancer." (PMID 33461604, 2021). "APC hypermethylation of high to moderate differentiation prostate cancer patients was shown associated with poor survival and patients with an unmethylated APC gene had better survival in metastatic CRC." (PMID 33369461, 2020). "The Adenomatous Polyposis Coli (APC) tumor suppressor is lost in many different cancers, including colorectal, breast, and prostate cancer, and its loss correlates with a decreased overall survival in cancer patients." (PMID 33105836, 2020). "We performed a search in Medline, Embase and CNKI database with GST, APC, RARbeta in combination with single nucleotide polymorphism, hypermethylation, prostate cancer and recurrence." (PMID 24086370, 2013). "APC hypermethylation was associated with an increase risk of prostate cancer biochemical recurrence (HR = 1.23, 95% CI = 1.07–1.42)." (PMID 24086370, 2013). "Although the critical role of Wnt signaling is demonstrated in the mutations of APC or β-catenin gene, such mutations are infrequent in prostate cancer, which counts 16% and 5%, respectively." (PMID 22511927, 2012). "In many cases of prostate cancer, adenomatous polyposis coli (APC) is mutated and hypermethylated to a silent form, and β-catenin is also frequently mutated to an active form." (PMID 24212796, 2011). "In addition to being associated with BCR, hypermethylation of APC was also correlated with prostate cancer mortality (HR = 1.57; 95% CI, 0.95–2.62)." (PMID 39783747, 2025). "Multiple cancer types have been found to have an abnormally methylated APC promoter, an indication that there might be a causal link between APC gene promoter 1A methylation and cancers including breast, lung, and prostate cancer." (PMID 37901797, 2023). "Moreover, RSPO2 gene fusions associated with elevated RSPO2 expression have been identified in prostate cancer patients, that were mutually exclusive with APC and CTNNB1 mutations." (PMID 34663878, 2021). "Genetic analysis studies have found APC mutations in 4% of patients with locoregional prostate cancer, that APC alterations were enriched in metastatic (15%) versus locoregional disease, and that 24% of patients with ductal carcinoma of the prostate had APC mutations." (PMID 32758244, 2020). "Previous studies have shown that mutations in β-catenin, APC, and other components of the destruction complex appear very rarely in prostate cancer cells, implicating other regulatory mechanisms for activating Wnt/β-catenin signaling in promoting prostate tumorigenesis." (PMID 31658259, 2019). "BRCA2 deficiency is a well-established predictor for response to PARP inhibition, while concurrent APC mutation—leading to Wnt pathway activation—has been linked to resistance against androgen deprivation and to neuroendocrine differentiation in advanced prostate cancer." (PMID 41395625, 2025). "However, mutations in β-catenin, APC, and other components of the destruction complex appear very rarely in prostate cancer cells, suggesting that other regulatory mechanisms underlie the activation of Wnt/β-catenin signaling in promoting prostate tumorigenesis." (PMID 31658259, 2019). "In a study analyzing the methylation patterns of 10 genes in the plasma of 42 patients with prostate cancer and 22 control patients, a significant hypermethylation difference was observed for four genes, including APC (p < 0.0001)." (PMID 39783747, 2025).